BRAF (B-Raf proto-oncogene, serine/threonine kinase)
Diseases named in the same sentence as BRAF in open-access papers (continued):
Sharing a sentence is not in itself a finding about the gene and the disease.
tumor (continued). "For the PICCOLO trial, of 861 patients enrolled in the treatment arms of interest for 349 (40.5%) tumour tissue was available for classification with 163 (46.7%) being RAS and BRAF wildtype." (PMID 34253874, 2021). "Two studies are designed to evaluate the DLTs and the ORR (NCT02974725 and NCT04417621, respectively) during combination therapy with Ribociclib and LXH254, a BRAF and CRAF inhibitor with antitumor activity in MAPK-driven tumor models." (PMID 34071228, 2021). "Based in our observations that the therapeutic effects of the anti-tumor antibodies TA99 can be enhanced by both ICB and MEKi targeted therapy, we tested the triple combination in the BRAF mutant YUMM1.7 cell line." (PMID 33520112, 2021). "Despite our current knowledge of the role of BRAF V600E in primary tumor in tumorigenesis of PTC, considering tumor heterogeneity, the relationship between BRAF V600E and clinical characteristics should also be evaluated in metastases." (PMID 33064665, 2020). "Whereas BRAF gene silencing showed limited cytotoxicity, the treatment of GAL-GNR-siGL2 + laser had a much stronger killing ability on tumor cells." (PMID 32449085, 2020). "Specifically, we evaluated each of the 4 common tumor markers (MSI, CIMP, BRAF, and KRAS) separately, as well as 3 pathways of carcinogenesis defined by combinations of those markers and tumor location." (PMID 32923935, 2020). "Thus, BRAF/MEK inhibitors could exert anti-epileptic as well as anti-tumor effects in PLNTY." (PMID 32811569, 2020). "Interestingly, BRAF mutation may appear in lymph node metastases with no expression in the primary tumor." (PMID 32668761, 2020). "Triple combination therapy with a BRAF inhibitor, a MEK inhibitor and pmel-1 adoptive cell transfer immunotherapy has been shown to increase T-cell infiltration into tumours and improve cytotoxicity in a murine model." (PMID 32645969, 2020). "In the BRAF wild-type subgroup, treatment with MEKi and anti-PD1 induced a tumor control rate of 83% and median progression-free survival of 7.1 months." (PMID 32585901, 2020). "Tumor recurrence was seen in four patients (one patient from “DNT-like” cluster 1 and three patients from “BRAF-GG” cluster 3)." (PMID 31919458, 2020). "To better understand the gene signature influencing patient survival, we conducted a subgroup analysis and mainly focused on tumor stage (clinical or AJCC stage) and molecular characteristics (BRAF and NRAS status)." (PMID 32411243, 2020). "CDK2 inhibitors that we previously identified in similar screens also showed protection in postmitotic cochlear cells whereas both BRAF inhibitors and CDK2 inhibitors are two known groups of anti-proliferative compounds in tumor cells." (PMID 33268358, 2020). "For targeted therapy with BRAF/MEK inhibitors, there is a known correlation between baseline tumor burden, response rate, and progression-free survival." (PMID 32052079, 2020). "However, the remaining three patients had BRAF mutations in their tumor, which we could not validate in plasma." (PMID 32486146, 2020). "Further, the gene expression profiling of the tumour exhibited a higher level of EPCAM, CK20, KRAS, AKT1, BRAF and CD133 expression, while lower levels of expression were observed in NANOG, MMP9 and APC genes." (PMID 33092235, 2020). "We also provide evidence that BRAF/MEK/ERK and CDK2 pathways, while key in tumor cells, play proapoptotic and stress-activating roles in postmitotic cochlear cells, an underappreciated feature of these pathways in postmitotic cells." (PMID 33268358, 2020). "Conversely, regorafenib, a novel oral MKI, blocks several protein kinases involved in the tumor angiogenesis (VEGFR-1, -2, and -3), tumor growth (KIT, RET, RAF-1, and BRAF), and metastasis (PDGFR-β, FGFR1) of cancer cells." (PMID 32466169, 2020).
tumor (continued). "To this end, we generated RNA-Seq data (polyA-enriched, TruSeq Stranded, 2 × 100 bp paired-end reads) from 22 fresh-frozen pediatric PA tumor samples, in which a KIAA1549:BRAF fusion had previously been identified by whole-genome sequencing (WGS)." (PMID 32476062, 2020). "It must be observed that BRAF inhibitors not only have poor activity against BRAF-WT cells but also result in activation of the Raf-MEK-ERK pathway, enhancing tumor proliferation and aggressiveness." (PMID 33348922, 2020). "Ganetespib inhibited tumor growth in mice xenografts, significantly potentiated the tumor growth inhibitory effect of BRAF and MEK inhibitors, and overcame mechanisms of primary and acquired resistance of melanoma cells to BRAF inhibitors." (PMID 31659567, 2020). "In contrast, a recent study found that BRAF inhibitors in combination with biguanide and phenformin (AMPK activators and complex I inhibitors) induced tumour regression." (PMID 32411231, 2020). "Early studies in melanoma have already investigated triple therapy with BRAF, MEK and PD-1 blockade and shown improved tumor control." (PMID 32457939, 2020). "BRAF and RAS, which exert their effects via the differential activation of MAPK and/or PI3K signaling, are the driver oncogenes in this tumor type." (PMID 32157211, 2020). "The molecular characterisation of CTCs to assess KRAS, BRAF and PIK3CA status has been achieved, which showed discordance of their status between the primary tumour and CTCs." (PMID 33209110, 2020). "Others also found a correlation between serial ctDNA analysis of BRAF and NRAS status and tumor response." (PMID 32010431, 2020). "Treatment with mutant BRAF inhibitor or MEK kinase inhibitor decreased the viability, proliferation and migration of the tumor cells and this effect was further increased by the combination of the two agents, but it did not induce cell death." (PMID 32591993, 2020). "We therefore propose that BRAF/MEK/ERK and CDK2 play proapoptotic roles in postmitotic cells while playing pro-proliferative roles in tumor cells." (PMID 33268358, 2020). "The rationale to combine an immune checkpoint inhibitor therapy with targeted therapy is that the treatment with a BRAF and MEK inhibitor renders the tumor microenvironment more immunoresponsive." (PMID 32092958, 2020). "Targeted therapies consist of anti-tumor angiogenesis, anti-EGFR therapy, tumor immunoregulatory inhibitors, anti-BRAF therapy, and anti-HER-2 therapy." (PMID 33153437, 2020). "Currently, tumor genotyping is critical as personalized treatment for EGFR, ALK, ROS1, BRAF in the first-line setting." (PMID 32525942, 2020). "Despite the positive immune impacts of inhibiting mutant BRAF or MEK, many patients still progress after a period of tumor control, leading to the combination of BRAF/MAPKi in the clinical setting." (PMID 33597954, 2020). "Further, two genetic types of carcinomas have been defined based on the manner in which the oncogenes BRAF and RAS promote tumor initiation and progression, and their relationship to the main pathways." (PMID 32157211, 2020). "Critically, vemurafenib directly alters immune-associated features of malignant cells, such that blocking mutant BRAF signaling results in the reduction of suppressive cytokine production and increased MHC expression by tumor cells." (PMID 33597954, 2020). "It inhibits the activity of target enzymes/factors located in tumour cells (CRAF, BRAF, V600E BRAF, c-KIT and FLT-3) and in tumour vasculature (CRAF, VEGFR-2, VEGFR-3 and PDGFR-β)." (PMID 32016844, 2020).
tumor (continued). "Studies in mice have also found that triple combination therapy with a BRAF inhibitor, MEK inhibitor and an anti-PD1 antibody produces greater anti-tumour activity than anti-PD1 monotherapy or any double combination amongst these therapies." (PMID 32645969, 2020). "Tumour tissue was analysed for MSI (microsatellite instability), CIMP (CpG island methylator phenotype), BRAF (B-Raf proto-oncogene serine/threonine kinase gene) and KRAS (Kirsten rat sarcoma viral oncogene homologue gene) mutations." (PMID 32225169, 2020). "Thus, the biological effects of MEK inhibition may be rapidly overcome by BRAF-wt tumours, perhaps due to the loss of negative feedback mechanisms under MEK inhibition." (PMID 30428063, 2019). "Molecular characteristics of the tumor that also affect patient survival, such as MSI, BRAF and KRAS, have only recently been included in the 8th edition of the UICC recommendations as additional indicators for clinical practice guidance." (PMID 31296182, 2019). "Univariate analysis by Kaplan–Meier survival analysis and log-rank test was performed using several factors, including age, primary tumour site, histological grade, histological type, KRAS, BRAF, PIK3CA and MSI status." (PMID 31406299, 2019). "Patients were diagnosed with 29 tumor types and harbored alterations in 43 oncogenes, most commonly ERBB2 (21.3%), PIK3CA (14.1%), and BRAF (8.7%)." (PMID 32914018, 2019). "TEAD deregulation affects well-established cancer genes such as KRAS, BRAF, LKB1, NF2, and MYC, and its transcriptional output plays an important role in tumor progression, metastasis, cancer metabolism, immunity, and drug resistance." (PMID 31212916, 2019). "For the 17 mCRC patients who received zFOLFIRI after prior bevacizumab plus FOLFIRI, 13 had mutant tumor KRAS, 3 had WT KRAS, and one had BRAF V600E." (PMID 30923702, 2019). "Tumor MMR immunohistochemistry, microsatellite instability (MSI), and BRAF sequencing were also investigated in specific cases." (PMID 31386297, 2019). "This is in stark contrast to the reported frequencies in the COSMIC database, where KRAS G12D and G12V, HRAS G12D, and BRAF V600E are reported to occur in 8/2585 (0.31%), 4/2585 (0.16%), 0/2159 (0%), and 0/1844 (0%) of IDC tumor samples." (PMID 30813596, 2019). "Using a basket trial setting of pan-cancer BRAF-V600E cell lines, we developed an O-PLS model to predict tumor cell sensitivity to vemurafenib and identified co-treatments to overcome inherent resistance." (PMID 31672130, 2019). "Efficacy of and resistance to targeted therapy with BRAF and MEK inhibitors are influenced by anti-tumor immunity." (PMID 31416487, 2019). "It is worth noting that although this tumor was progressing on the PD1 inhibitor pembrolizumab, this patient had progressed on prior BRAF/MEK inhibitor combination therapy, presumably due to the activating NRAS Q22K mutation." (PMID 31795494, 2019). "As previously presented, it has the capacity to crosstalk with RAS/BRAF/MEK pathway and ligand secretion by tumor stroma, inducing cancer cell migration and in vitro tumorigenesis." (PMID 31430969, 2019). "The rationale behind this association is that the MEK inhibition prevents the rebound activation of MEK and ERK pathway after BRAF inhibition; this combination results in enhancement of BRAF-MEK-ERK pathway inhibition and anti-tumour activity." (PMID 31443283, 2019).
tumor (continued). "The absence of the BRAF mutation in the juice of case #10 suggests that the fluid contained little DNA arising from the tumor, and that the KRAS mutation may have its origin somewhere else, most likely in the tail region of the pancreas drained by the distal duct." (PMID 30611220, 2019). "While recurrent oncogenic lesions in BRAF (pV600) and N/K/HRAS (pG12/13, p.Q61) predominate within the RAS-MAPK pathway, they are rarely identified in conjunction within any single tumor specimen." (PMID 30651601, 2019). "Without any known actionable mutations were detected in the five samples, such as EGFR, KRAS, BRAF, HER2, and EML4‐ALK in the tumor tissues." (PMID 30941903, 2019). "The BRAF, NRAS and NF1 driver alterations all activate the mitogen‐activated protein kinase (MAPK) pathway and generally occur at the earlier stages of tumour evolution." (PMID 30511391, 2019). "Although it has been shown that the MAPK signalling cascade can increase VEGF expression and that BRAF mutation might also modulate tumour response to anti-angiogenic treatments, the value of bevacizumab in BRAF-mt patients has not yet been clinically demonstrated." (PMID 31353365, 2019). "While searching for genes commonly altered in LUAD from the “CANCER” tab in SL-BioDP, it shows that the gene BRAF is upregulated in LUAD tumor samples (logFC > 6, p-value < 0.001), compared to solid tissue normal samples in TCGA tumor sample data." (PMID 31671773, 2019). "We included the prediction of an image only if the probability of either BRAF or RAS class was at least 80%; and reported the prediction of a tumor only if at least 80% image tiles derived from the slide agreed with it." (PMID 31614962, 2019). "By IFN-γ production assay and CTL assay, BRAF-specific immune response was illustrated and a large amount of CTL infiltration was observed within the tumour microenvironment." (PMID 31617076, 2019). "Overall, these data suggest that MAPK inhibition can lead to dependence on MCL-1 in vivo and that therapeutic targeting using BRAF and MCL-1 inhibitors can induce profound tumor (in some cases pathologic complete responses) in tumor-bearing mice." (PMID 31727958, 2019). "From this cohort, we tested the predictive value of common clinicopathological parameters (ulceration, mitotic count and tumor regression) and FMNL-2, ezrin and BRAF V600E immunoreactivity, for sentinel node involvement and survival." (PMID 31039200, 2019). "The treatment then was switched to BRAF-MEK inhibitors dabrafenib and trametinib at 8 months postoperatively and a marked decrease in residual tumor and leptomeningeal disease was observed 14 months after the initial surgery." (PMID 31181803, 2019). "BRAF-MAF was found to be in the range of 2.2–80.3%, while NRAS-MAF was in the range of 4.6–71.0%, indicating log range differences between various tumor samples." (PMID 31391014, 2019). "The rapid development of resistance to BRAF/MEK inhibitors and their dynamic impacts on the tumor microenvironment and systemic antitumor immunity should also be considered to determine the sequencing and scheduling of the combination." (PMID 30100909, 2018). "The authors analyzed inter- and intra-tumor heterogeneity by means of single cell RNA-seq, identifying CDK4, highly expressed in most of the sub-clones derived from BRAF wt/NRAS wt tumors, as a potential therapeutic target." (PMID 29491834, 2018). "The combined inhibition of BRAF and ALK stopped tumour growth, supporting the clinical relevance of our findings." (PMID 30290811, 2018). "KRAS, NRAS and BRAF are kinases involved in the RAS-RAF-MAPK signaling pathway and also potential tumor-driven genes." (PMID 30416987, 2018). "Sorafenib is an oral multikinase inhibitor that mainly targets kinases involved in tumor cell growth and angiogenesis such as Raf kinases (CRAF, BRAF, V600E BRAF) and tyrosine kinases (FLT3, Kit, VEGFR2/3 and PDGFRB)." (PMID 30459932, 2018).
tumor (continued). "Tailoring existing therapies based on tumor sidedness, KRAS, MSI, or BRAF status as well as individualizing treatments for elderly or DM patients represent our current efforts to provide more personalized care in oncology." (PMID 30519549, 2018). "Some reports showed that the BRAF V600E can induce MMPs; a positive correlation has been reported between BRAF V600E and MMP-9 and MMP-2 expressions, both being correlated with tumor extrathyroid extension." (PMID 30509240, 2018). "However, BRAF-V600E mutations and copy number changes have also been reported in DNETs, and there is a general lack of consensus regarding the genetic background of these tumours." (PMID 29058119, 2018). "Many studies have found that higher expression of Braf mutant protein can predict aggressive tumor behavior in PTC, and BRAF V600E IHC has high practical value for the detection of the BRAF V600E mutation in primary and metastatic PTC." (PMID 30005075, 2018). "Compared with triple-negative (ie, MSI-negative, KRAS and BRAF wild-type) cancers, MSI-negative tumours with KRAS (HR 1·35 [95% CI 1·11–1·64]; p=0·003) or BRAF (2·02 [1·47–2·76]; 1·20 × 10−5) mutations were associated with worse prognosis." (PMID 30042065, 2018). "Like other cases of secondary HS, a clonal relationship between the primary PCM and secondary tumor in current case was confirmed by FISH and NGS analyses showing IGH-MAF gene rearrangement, and similar genomic alterations in KRAS, BRAF and MAK3K6." (PMID 29463311, 2018). "This tumor had histologic and immunophenotypic features similar to the recently described PLNTY and proved BRAF V600E mutant." (PMID 29701169, 2018). "Combination of BRAF inhibitor (PLX4720) and Src tyrosine receptor/Bcr-Abl family inhibitor (Dasatinib) showed reduced tumor size, increased immune cell infiltration and induced apoptosis in an orthotopic ATC mouse model." (PMID 30352606, 2018). "In other words, ERK-dependent tumor cells, including cancers driven by mutant RTK, RAS, BRAF, or MEK proteins, will have a vulnerability to hyperactivated ERK and that vulnerability can potentially be exploited by inhibition of feedback regulators like DUSP6." (PMID 30475204, 2018). "Further, these studies showed that MYC inactivation restored RAS/BRAF-induced senescence, indicating that continuous MYC signaling is necessary for RAS/BRAF-induced tumorigenesis and tumor progression." (PMID 30526305, 2018). "As BRAF mutant/MSS cancers frequently metastasize, clarification of the expression of these markers is important for accurate diagnosis of the primary tumour site." (PMID 30598662, 2018). "A second biopsy was gathered from a mCRC patient whose tumour carried genetic alterations in RNF43 and BRAF genes, and clinically responded and then relapsed to EGFR blockade with cetuximab in combination with the BRAF inhibitor encorafenib." (PMID 29895949, 2018). "Later, numerous other studies revealed that, despite the frequently high degree of concordance between alterations in different tumor areas, analysis of a single tumor block led to the incorrect assignment of KRAS and BRAF status in 10–30% of cases." (PMID 30477151, 2018). "Meanwhile, there was a high concordance between primary CRCs and corresponding metastases, demonstrating that RAS/BRAF abnormalities emerged early in CRC tumorigenesis, and tumor cells kept their MSI status during development." (PMID 29643917, 2018).